ATG14 (autophagy related 14)
Diseases named in the same sentence as ATG14 in open-access papers (continued):
Sharing a sentence is not in itself a finding about the gene and the disease.
COVID-19 (2 papers, 2022 to 2025). A disease caused by infection with severe acute respiratory syndrome coronavirus 2. "Our findings suggest that targeting the interaction between NSP6 and the ATG14/Beclin1/VPS34 complex or MLN1 could serve as a promising therapeutic avenue in the treatment of COVID-19." (PMID 40332329, 2025). "MiRNAs that were downregulated in serum of COVID-19 patients mainly target genes promoting angiogenesis (e.g., VEGFA, ANGPT2, COL4A1, FGF2, ZEB1), apoptosis, autophagy, stress response (e.g., ATG12, ATG14, ATG2B, SOD2, TXNIP), and inflammation (e.g., CXCL9, CXCL10, IL1R1, TNF)." (PMID 36032130, 2022).
Infertility (2 papers, 2024 to 2025). "Loss of ATG14 in the oviduct resulted in severe structural abnormalities, compromising its cellular integrity, and ultimately leading to embryo retention and infertility." (PMID 40100261, 2025). "Loss of ATG14 in the oviduct resulted in severe structural abnormalities, compromising its cellular integrity, ultimately leading to embryo retention and infertility." (PMID 38562843, 2024). "Atg14 loss in the female reproductive tract (FRT) results in infertility." (PMID 40100261, 2025). "Based on the normal ovarian morphology, we posited that the infertility observed in females with Atg14 cKO status could be attributed to compromised uterine functioning." (PMID 38562843, 2024).
influenza (2 papers, 2018 to 2022). An acute viral infection of the respiratory tract, occurring in isolated cases, in epidemics, or in pandemics; it is caused by serologically different strains of viruses (influenzaviruses) designated A, B, and C, has a 3-day incubation period, and usually lasts for 3 to 10 days. "Deletion of autophagy genes including Epg5, Atg14, FIP200, Atg5 and Atg7 led to influenza resistance." (PMID 36042265, 2022).
lung carcinoma (2 papers, 2016 to 2025). "Here, it was found that ING5 overexpression in vivo and vitro induced the autophagy of lung cancer cells with ATG13, ATG14 and Beclin-1 overexpression, indicating that ING5-induced autophagy was dependent on Beclin-1 and belonged to canonical pathway." (PMID 27409347, 2016).
osteoporosis (2 papers, 2022 to 2025). A condition of reduced bone mass, with decreased cortical thickness and a decrease in the number and size of the trabeculae of cancellous bone (but normal chemical composition), resulting in increased fracture incidence. "ATG14 contributed to active chondrocyte differentiation and reduced oxidative injury to block osteoporosis." (PMID 40584820, 2025). "All in all, we, at the first time, demonstrated that miR-152-5p/ATG14/ROS axis was involved in osteogenic differentiation which may contribute to osteoporosis." (PMID 35883156, 2022). "Our data suggest that miR-152-5p is the first identified to regulate osteogenic differentiation by directly targeting autophagy-related protein ATG14 and regulating oxidative stress, and inhibition of miR-152-5p may provide an effective therapeutic method for osteoporosis." (PMID 35883156, 2022). "Our data suggest that miR-152-5p is the first identified to regulate osteogenic differentiation by directly targeting autophagy-related protein ATG14 and regulating oxidative stress and therapeutic inhibition of miR-152-5p may be an efficient anabolic strategy for osteoporosis." (PMID 35883156, 2022).
acute myeloid leukemia (1 paper, 2023). Acute myeloid leukemia (AML) is a group of neoplasms arising from precursor cells committed to the myeloid cell-line differentiation. "Autophagy-related proteins such as ULK1, ATG3, ATG5, ATG13, and ATG14 were markedly expressed in various acute myeloid leukemias when comparing the microarray-based expression profiling of distinct ATG proteins from human AML samples with the human normal hematopoiesis." (PMID 37180758, 2023).
asthma (1 paper, 2020). "Moreover, the formation and activation of the autophagy-specific ATG14-Beclin1-p150-PI3-Kinase complex, and the autophagy initiation and development, would be promoted during asthma, during which the T cells are activated and the cytokine secretion is affected by the B cells." (PMID 33643037, 2020).
Autoimmunity (1 paper, 2025). The occurrence of an immune reaction against the organism's own cells or tissues. "This study shows that Vps34 and Atg14 regulate signaling events that control effector Treg heterogeneity and functional adaptation, with pathophysiological consequences on autoimmunity and anti-tumor immunity." (PMID 40215232, 2025). "In contrast, our study shows that Atg14 but not Uvrag deficiency in Tregs only partially recapitulates the effects of Vps34 inhibition, including the development of a mild lymphoproliferative disease (but not Scurfy-like autoimmunity) and enhanced anti-tumor immunity." (PMID 40215232, 2025).
bladder cancer (1 paper, 2022). "Furthermore, increased SNHG1 expression enhances bladder cancer cell proliferation, invasion, and autophagy via the miR-493-5p/ATG14/autophagy pathway." (PMID 35669241, 2022).
cardiac hypertrophy (1 paper, 2025). "Deletion of the autophagy gene ATG14 reportedly results in a shortened lifespan and cardiac hypertrophy." (PMID 39993967, 2025).
Chagas disease (1 paper, 2021). A parasitic infection caused by Trypanosoma cruzi. "To address this, here we investigated the role of the variant subunits VPS38/UVRAG (complex II, endocytosis) and ATG14 (complex I, autophagy) in the biogenesis of the yolk organelles in the insect vector of Chagas Disease Rhodnius prolixus." (PMID 34492013, 2021).
colon adenocarcinoma (1 paper, 2024). "We analyzed the correlation between KRAS mutational status and expression of several autophagy genes, including MAP1LC3B, ATG5, ATG10, ATG13, and ATG14 in both COAD (colon adenocarcinoma) READ (rectum adenocarcinoma) as well as normal tissue." (PMID 39057088, 2024).
coronary artery disease (1 paper, 2018). "Interestingly, in the cardiac myocardial infraction or coronary artery disease model, ATG14 is required for the angiogenesis via Becn1–Vps34–ATG14 complex, which is a novel agent for treatment of acute ischemia-mediated myocardial injury via handling revascularization." (PMID 29962971, 2018).
Hepatic steatosis (1 paper, 2025). Steatosis is a term used to denote lipid accumulation within hepatocytes. "Specifically, Atg14 liver-specific-knockout mice subjected to a high-fat diet developed severe hepatic steatosis; however, overexpression of Atg14 in knockdown mice decreased the accumulation of lipid droplets." (PMID 41439967, 2025).
herpesvirus infection (1 paper, 2024). "Additionally, myeloid-specific knockout of several autophagy genes (RB1CC1, Beclin1, ATG3, ATG5, ATG7, ATG14, or ATG16L) in animals subjected to herpesvirus infection results in elevated inflammation and prevented viral reactivation from latency." (PMID 38447109, 2024).
Huntington disease (1 paper, 2016). Huntington disease (HD) is a rare neurodegenerative disorder of the central nervous system characterized by unwanted choreatic movements, behavioral and psychiatric disturbances and dementia. "We also show that ATG14-associated Vps34 activity and ULK1-mediated phosphorylation of ATG14 and Beclin 1 are compromised in the Q175 mouse model of Huntington’s disease." (PMID 27938392, 2016). "We generated anti-phosphorylated ATG14 antibody to determine ATG14-mediated autophagy regulation; we employed Huntington’s disease (HD) genetic cell models and animal models as well as autophagy reporter animal model to understand autophagy signaling and regulation in vivo." (PMID 27938392, 2016).
intracranial aneurysm (1 paper, 2022). "Another study suggested that downregulation of miR-29b induced VSMC phenotypic modulation by directly activating ATG14-mediated autophagy, which was involved in the pathogenesis of intracranial aneurysm." (PMID 35136037, 2022).
liver cancer (1 paper, 2024). An epithelial or non-epithelial malignant neoplasm that arises from the liver. "We found that the relationships between IFRD1, ATG14, and H1.0 were intact in vivo liver cancer tissues, suggesting that the signaling pathway uncovered in vitro is clinically relevant." (PMID 38802351, 2024).
lymphoma (1 paper, 2025). A malignant (clonal) proliferation of B- lymphocytes or T- lymphocytes which involves the lymph nodes, bone marrow and/or extranodal sites. "Compared with those in control tissue, lymphoma showed significant increases of in LC3B (LC3BI represents early autophagy, while LC3BII represents autophagic flux), autophagy related 14 (Atg14) and Beclin-1 levels, and a decrease in p62 (sequestosome 1) levels." (PMID 40296899, 2025).
nasopharyngeal carcinoma (1 paper, 2025). A carcinoma arising from the nasopharyngeal epithelium. "Previous studies have shown, upregulation of lncRNA HAGLROS enhances nasopharyngeal carcinoma development by modulating PI3K/AKT/mTOR signaling mediated by miR-100/ATG14 axis." (PMID 40756984, 2025).
osteoarthritis (1 paper, 2021). A noninflammatory degenerative joint disease occurring chiefly in older persons, characterized by degeneration of the articular cartilage, hypertrophy of bone at the margins and changes in the synovial membrane. "Our previous study found that has_circ_0005567 was low expressed in osteoarthritis and overexpression of has_circ_0005567 can promote chondrocyte autophagy by regulating mir-495/ATG14 axis, thereby inhibiting chondrocyte apoptosis and osteoarthritis progression." (PMID 34652255, 2021).
ovarian tumor (1 paper, 2023). "EGR1-MIR152 was shown to regulate cisplatin-mediated autophagy in ovarian tumor cells via ATG14 targeting." (PMID 37098542, 2023). "MiR-29c-3p impeded autophagy and CDDP resistance via FOXP1/ATG14 axis in ovarian tumor cells." (PMID 37098542, 2023). "EGR1 regulated miR-152 and ATG14, which then improved CDDP sensitivity in ovarian tumor cells." (PMID 37098542, 2023).
Parkinson disease (1 paper, 2019). A progressive degenerative disorder of the central nervous system characterized by loss of dopamine producing neurons in the substantia nigra and the presence of Lewy bodies in the substantia nigra and locus coeruleus. "When we compared the Z-scores obtained from these two TWAS, we found that 12 genes discovered in International Parkinson Disease Genomics Consortium (IPDGC) cohort (e.g., MAPT, SNCA, ATG14, DVL3, and MTOR) could be replicated." (PMID 30824768, 2019).
pneumococcal infection (1 paper, 2020). Infections with bacteria of the species streptococcus pneumoniae. "We demonstrated that CbpC inhibited autophagic flux; however, a detailed time course of the changes of CbpC‐driven autophagic activation and subsequent Atg14 depletion during pneumococcal infection has not been fully revealed." (PMID 32239622, 2020).
polycystic ovary syndrome (1 paper, 2024). A disorder that manifests as multiple cysts on the ovaries. "Recent reports indicate a substantial reduction in ATG14 levels within the endometrium of individuals diagnosed with polycystic ovary syndrome." (PMID 38267415, 2024).
sarcopenia (1 paper, 2023). Progressive decline in muscle mass due to aging which results in decreased functional capacity of muscles. "Notably, Fyn plays an active role in the development of sarcopenia by decreasing the Vps34/p150/Beclin1/Atg14 complex and consequently inhibiting macroautophagy in the skeletal muscle." (PMID 37190106, 2023).
steatosis (1 paper, 2021). Increased lipid within the cytoplasm of cells. "Within nutrient overload steatosis models, 13 different experiments were analyzed from 9 manuscripts which genetically modulated the expression of ATG7, ATG4B, ATG14, TFEB, FIP200, and ULK1." (PMID 33937257, 2021).
tumor (16 papers, 2011 to 2026). "Using the ratio of non-synonymous to synonymous mutations (dN/dS value) for missense and truncating mutations, we found that many of the driver genes, including CBFB and ATG14, are potential tumor suppressor genes with high truncating mutations." (PMID 36831585, 2023). "USP1 deubiquitinates and stabilizes ATG14, thus remarkably promoting malignant features, such as cell proliferation, migration, autophagy, and tumor growth in PDAC." (PMID 39814232, 2025). "ATG14 has been found to control tumor resistance mechanisms in pancreatic cancer, gastric cancer, and ovarian cancer, playing a crucial role in treatment prognosis." (PMID 39108268, 2024). "BECN1 and ATG14 genes were responsible for the vesicle nucleation stage, and were related with tumor progression." (PMID 30460069, 2017). "Moreover, ablation of USP1 diminished the expression of ATG14 in tumor tissues, which suggested that USP1 promotes tumor growth via upregulating ATG14 expression." (PMID 39814232, 2025). "Accordingly, mice with Treg-specific loss of Atg14, but not Uvrag, had moderately disrupted immune homeostasis and reduced tumor growth, with Vps34- or Atg14-dependent gene signatures also being elevated in intratumoral Tregs from human cancer patients." (PMID 40215232, 2025). "To explore whether Atg14 or Uvrag mediates Treg-dependent suppression of anti-tumor immunity, we next inoculated Foxp3CreAtg14fl/fl or Foxp3CreUvragfl/fl mice and their respective control counterparts with MC38 tumors." (PMID 40215232, 2025). "Furthermore, LINC00518’s overexpression promotes tumor growth in multiple myeloma cells by downregulating miR-140–5p expression and upregulating ATG14 expression." (PMID 39108268, 2024). "Similarly, ATG2A or ATG14 downregulation in Hep3B cells counteracted the stimulative effect of YTHDF1 overexpression on tumor growth." (PMID 33619246, 2021). "We found that in all four human cancer types, there were enrichments in the Vps34-activated and Atg14-activated gene signatures in intratumoral Tregs compared to their non-tumor tissue counterparts, indicating that Vps34 and Atg14 may regulate the function of intratumoral Tregs in human cancer." (PMID 40215232, 2025). "We demonstrated that ATG14 expression was elevated in tumor tissues compared with normal tissues, and elevated ATG14 expression was correlated with poor prognosis, suggesting that ATG14 may be involved in tumor progression in PDAC." (PMID 39814232, 2025). "For example, long non-coding RNA PVT1 is reported to be closely related to autophagy and has been proved to affect tumor autophagy via miR-365/ATG3, miR-20a-5p/ULK1, miR-619-5p/ATG14 or multiple axes." (PMID 34823534, 2021). "For example, even though ATG14 was found to have high levels of truncating mutations, suggesting its potential role as a tumor suppressor, knocking-down experiments found that suppressing ATG14 does not always promote tumor growth." (PMID 36831585, 2023). "The reader YTHDF1 promotes tumor progress by influencing ATG2A, ATG14, and HIF-1α." (PMID 36059442, 2022). "This includes the tumor suppressor LKB1, AMPKα1, ULK1, Atg14 and Beclin-1." (PMID 36578014, 2022). "Finally, we found that targeting Vps34 or Atg14, but not Uvrag, in Tregs reduced tumor growth." (PMID 40215232, 2025).
infection (12 papers, 2017 to 2026). The state of being infected such as from the introduction of a foreign agent such as serum, vaccine, antigenic substance or organism. "The LTR association remained lower for Mtb WT and ΔesxBA in ATG14 KO iPSDM even after 24 h of infection." (PMID 36959508, 2023). "Our data show that ATG7- and ATG14-dependent restriction and induction of cell death is primarily associated with Mtb WT infection." (PMID 36959508, 2023). "The percentage of Gal3-positive phagosomes containing Mtb WT and ΔcpsA was higher at 2 h after infection in iPSDM deficient for ATG14 compared with WT iPSDM." (PMID 36959508, 2023). "Stereological analysis of cytosolic bacteria further confirmed that a higher fraction of Mtb WT was localized in the cytosol of ATG14-deficient iPSDM 48 h post infection." (PMID 36959508, 2023). "Conversely, after inhibitor infection, Hif1a (p=0.048), Fzd6 (p<0.01), and Gcnt2 (p<0.01) were increased and Atg14 (p=0.042) increased." (PMID 38770735, 2024). "In Procambarus clarkii, ATG14 expression was initially upregulated upon WSSV infection and then stabilized." (PMID 38902611, 2024). "Similar to the ATG7 KO iPSDM infected with Mtb WT, most of the ATG14 KO iPSDM underwent cell death after Mtb WT infection, precluding fixed cell image-based analysis." (PMID 36959508, 2023). "In contrast, in ATG14 KO iPSDM, the activity of the promoter remained low even after 48 h of infection." (PMID 36959508, 2023). "Cell death increased exponentially after 72 h of infection in ATG14 KO iPSDM, which correlated with high bacterial loads." (PMID 36959508, 2023). "When MEFs (mouse embryonic fibroblast cells) stably expressing hemagglutinin (HA)‐tagged Atg14 (MEFs/HA‐Atg14) were infected with S. pneumoniae R6 ∆cbpF/pCbpFR6‐FLAG, a CbpFR6–FLAG–HA–Atg14 interaction was clearly detected during infection." (PMID 32239622, 2020). "However, when compared with ATG7 KO macrophages, the replication and cell death phenotype in iPSDM lacking ATG14 was more pronounced at 96 h post infection (30% ATG7 KO versus 50% in ATG14 KO cell death after 96 h infection)." (PMID 36959508, 2023). "In summary, we showed that S. pneumoniae manipulates the selective autophagy system to spatiotemporally regulate the level of Atg14 and dampening antibacterial xenophagy induced at later stages of infection, thereby increasing its viability and ability to invade more deeply into host tissues." (PMID 32239622, 2020). "A previous study has demonstrated that infection with cp BVDV induced autophagy and significantly upregulated the mRNA and protein levels of autophagy-related genes, Beclin1 and ATG14 in MDBK cells at 12 h post infection." (PMID 37900320, 2023). "After 2 h of infection, the mean intensity of LTR was lower for both Mtb WT and ΔesxBA in ATG14 KO infected iPSDM." (PMID 36959508, 2023). "Our study showed that the expression of autophagy-related genes ULK1, ATG13, ATG101, Beclin-1, ATG14, MAP1LC3A, and MAP1LC3B was significantly increased and that SQSTM1 was decreased in the muscle with pathogen infection." (PMID 33574492, 2021). "Therefore, we hypothesized that S. pneumoniae could promote CbpC‐driven selective autophagy during early infection and that CbpC–Atg14 binding would lead to Atg14 degradation, which, in turn, would reduce autophagosome–lysosome fusion and bacterial degradation." (PMID 32239622, 2020). "Furthermore, compared to non-infection, SARS-CoV-2 infection decreased the interaction between ATG14 and STX18." (PMID 38245527, 2024). "After infection of MDM, there were higher replication rates with both Mtb WT (2.6-fold) and ΔesxBA (0.3-fold) in MDM lacking ATG14 than in WT or ATG7-deficient MDM." (PMID 36959508, 2023). "The results indicated that punicalagin (40 μM) could upregulate the autophagy‐related protein ATG14 at 24 h post‐infection compared to the MAB‐infected THP‐1 without punicalagin treatment." (PMID 41085014, 2026).
infection (continued). "Similarly to what we observed at 96 h post infection, the ratio of PI-positive iPSDM lacking ATG14 was six-fold higher than in WT iPSDM." (PMID 36959508, 2023).